ENSG00000251830
Synonyms: LOC124900220
Gene: Small nucleolar RNA gene on chromosome 6 (24,166,273 to 24,166,374, forward strand). Ensembl gene ENSG00000251830.
Gene Ontology:
Biological process: RNA processing
Cellular component: nucleolus
Homologues: Orthologues: zebrafish SNORD46 (65% identical). Paralogues in human: SNORD46 (83% identical).